SOST (sclerostin)
Diseases named in the same sentence as SOST in open-access papers (continued):
Sharing a sentence is not in itself a finding about the gene and the disease.
osteoporosis (continued). "Such neutralizing Sclerostin antibodies may be used for future anabolic treatment of osteoporosis." (PMID 23638027, 2013). "Thus, sclerostin may be an effective therapeutic target for osteoporosis." (PMID 39606935, 2025). "European-focused GWAS have identified key loci for osteoporosis, including WNT signaling (SOST, LRP5) and RUNX2 transcriptional regulation." (PMID 40411668, 2025). "A monoclonal antibody against sclerostin, romosozumab, can significantly increase the BMD of postmenopausal women and men with osteoporosis." (PMID 40464222, 2025). "This study presents a novel, cost-effective osteoporosis vaccine with dual preventive and therapeutic capabilities, derived from the high-affinity binding epitope of ROMO to SOST." (PMID 41403949, 2025). "Anti-sclerostin monoclonal antibodies and anti-DKK1 monoclonal antibodies are inhibitors of WNT antagonists and are used to treat osteoporosis by promoting osteogenesis." (PMID 40772209, 2025). "Specifically, inhibitors of the Wnt signaling pathway, including sclerostin, DKK1, WIF1, and SFRP, negatively regulate bone formation during osteoporosis." (PMID 39606935, 2025). "The preliminary safety information for the humanized anti-sclerostin monoclonal antibody, romosozumab, stemmed mainly from the FRAME (the fracture study in postmenopausal women with osteoporosis), ARCH, and BRIDGE clinical trials." (PMID 40429697, 2025). "In fact, FGF23 and sclerostin are currently being used as therapeutic targets after the development of antibodies against these proteins for the treatment of XLH and osteoporosis, respectively." (PMID 38634076, 2024). "Our previous study has also shown that NTX mitigates osteoporosis-related markers by reducing the levels of TRAIL, adiponectin, and sclerostin in BDL-induced osteoporosis." (PMID 38167957, 2024). "Sclerostin, a product of the SOST gene, inhibits Wnt signaling and is being investigated for osteoporosis." (PMID 39295699, 2024). "Interleukin-1 beta (IL-1β), sclerostin, osteoprotegerin (OPG), and interleukin-34 (IL-34) emerged as significant biomarkers in GCF, and they were mainly from periodontitis and osteoporosis." (PMID 39410587, 2024). "The anti-sclerostin antibody, romosozumab, and anti-RANKL antibody, denosumab, are now widely used for osteoporosis therapy; however, antibody drugs are still expensive for a large number of patients worldwide." (PMID 39768281, 2024). "Pharmacological inhibition of sclerostin and DKK-1 by monoclonal antibodies is one of the novel therapy for osteoporosis that is capable to promote new bone tissue growth." (PMID 37703870, 2023). "Moreover, the Active-Controlled Fracture Study in Postmenopausal Women With Osteoporosis at High Risk (ARCH) study, revealed an increased risk of serious adverse cardiovascular events in postmenopausal women during the first year treatment with anti-sclerostin antibody." (PMID 37919715, 2023). "The Wnt classical pathway inhibitors, such as sclerostin antibodies and dickkopf 1 (DKK1), have shown clinical potential for the treatment of osteoporosis." (PMID 38033331, 2023). "Romosozumab (EVENITY), an antibody to sclerostin which activates WNT signaling, is an FDA-approved therapy for osteoporosis." (PMID 36814601, 2023). "Osteoporosis increases the apoptosis, adipogenic differentiation, and levels of RANKL and sclerostin of bone marrow mesenchymal stem cells and osteoblasts." (PMID 36570136, 2022). "BMD showed a significant positive correlation with sclerostin levels; therefore, SCI patients with severe osteoporosis should have lower sclerostin levels." (PMID 35742035, 2022). "Since the sclerostin antibody romosozumab is now an established and approved treatment for severe postmenopausal osteoporosis, it will be of interest whether this drug is particularly effective in disuse osteoporosis or, more generally, how effective the drug is under different loading conditions." (PMID 33738515, 2022).
osteoporosis (continued). "The identification of genes involved in skeletal diseases can result in novel treatments for osteoporosis, as was the case for denosumab, an anti-RANKL monoclonal antibody and romosozumab, an antibody against the Wnt-inhibitor sclerostin, SOST." (PMID 35205324, 2022). "Romosozumab is a humanized antibody against SOST and has been approved by the US FDA for the treatment of osteoporosis." (PMID 36581888, 2022). "Anti-sclerostin antibody (Scl-Ab), such as romosozumab (AMG785), is well-studied in postmenopausal women with osteoporosis." (PMID 35328533, 2022). "Pharmacological inhibition of sclerostin and DKK-1 by monoclonal antibodies has been explored as a potential therapy for osteoporosis, fracture healing, and other bone disorders." (PMID 36506070, 2022). "Other studies have also shown that pathological values of both sclerostin and DDK1, essential mediators in the Wnt/b-catenin pathway, are related to osteoporosis in patients with pSS." (PMID 33917955, 2021). "Emerging osteoporosis therapies utilize novel mechanisms, including monoclonal antibodies against RANKL, DKK1, and sclerostin." (PMID 34065531, 2021). "Both SOST and DKK1 antagonism using monoclonal antibodies has emerged as a therapeutic approach to treat osteoporosis." (PMID 34737712, 2021). "Although potential markers of osteoporosis in diabetic women have been previously proposed, here we propose IGF-1 and sclerostin as potential markers as well." (PMID 34690653, 2021). "Reportedly, as blood sclerostin levels increase, BMD decreases in postmenopausal women, and postmenopausal women with significantly increased serum Dkk-1 exhibit more significant osteoporosis." (PMID 34034718, 2021). "Pharmacological targeting of osteoblasts or the balance between osteoblasts and osteoclasts is already an accepted strategy for the treatment of osteoporosis, and the FDA-approved osteoporosis drugs target RANKL, parathyroid hormone, and sclerostin." (PMID 34073480, 2021). "A sclerostin (SOST) antibody and interferon γ (IFNγ) also have therapeutic potential in treatment of osteoporosis." (PMID 33413646, 2021). "The RA + osteoporosis group had elevated sRANKL levels (p = 0.005), higher sRANKL/OPG ratio (p = 0.017), decreased DKK-1 (p = 0.028), and lower SOST levels (p < 0.001)." (PMID 34497849, 2021). "Indeed, targeting sclerostin protein with neutralizing antibodies is incredibly effective at increasing bone mass, and Romosozumab, a humanized monoclonal antibody targeting sclerostin, has been FDA approved to treat osteoporosis in post-menopausal women at a high risk for fracture." (PMID 33779549, 2021). "Hypermethylation of CpG islands of bone-inhibitory factors, like SOST, dickkopf-1 (DKK1), and Wnt inhibitory factor 1 (WIF1) are present in postmenopausal women with osteoporosis." (PMID 32664681, 2020). "Sclerostin antibody romosozumab clears a phase III trial with satisfactory outcomes and already got approval for osteoporosis treatment." (PMID 32733380, 2020). "Inactivating monoclonal antibodies against SOST, a inhibitor of the negative regulation of WNT/β-catenin signaling, has been shown to be a candidate for the prevention and treatment of osteoporosis (Rossini, Gatti & Adami, 2013)." (PMID 31086734, 2019). "Hence, strategies for reducing circulating sclerostin may prove valuable in treating osteoporosis." (PMID 31170332, 2019). "Sclerostin correlates with BMD and bone metabolism markers in hemodialysis patients and participates in osteoporosis during early CKD." (PMID 31027235, 2019). "Osteoporosis induced control animals (OVX PBS) displayed a more numerous and intense sclerostin staining (p = 0.018)) compared to the Sham operated, healthy animals." (PMID 30366476, 2018). "This information is mandatory as anti-sclerostin and anti-DKK1 monoclonal antibodies emerge as very promising pharmaceuticals in the treatment of osteoporosis." (PMID 28493902, 2017).
osteoporosis (continued). "The restricted expression of sclerostin in bone and the lack of complications in organs other than the skeleton in humans and animals with sclerostin deficiency made this protein an attractive target for the development of a novel anabolic therapy for osteoporosis." (PMID 27016922, 2016). "Osteoporosis is a chronic disease requiring chronic treatment and it is not yet known whether long-term treatment with a sclerostin inhibitor will be associated with a sustained anabolic effect on bone or whether initial treatment need to be followed by another agent." (PMID 27016922, 2016). "Patients with sclerosteosis and van Buchem disease have high bone mass due to downregulation of sclerostin, suggesting that a therapeutic agent that downregulates sclerostin in a controllable fashion might be a potent osteoanabolic treatment for patients with osteoporosis." (PMID 21234374, 2010). "Although our study confirmed that sclerostin correlates with BMD, its predictive value for osteoporosis may depend on broader physiological contexts, including comorbid conditions and physical activity status." (PMID 41594249, 2026). "Sclerostin and DKK1 can competitively bind to LRP5/6, a co-receptor in the Wnt signaling pathway, and inactivate it by regulating the transcription of downstream target genes, eventually inducing osteoporosis." (PMID 39606935, 2025). "Sclerostin, an osteocyte-specific glycoprotein that inhibits the canonical Wnt pathway (similarly to DKK1 by binding to LRP5/6) is the target of romosozumab, the humanized monoclonal antibody treatment for osteoporosis." (PMID 40700291, 2025). "SOST levels in BPC are correlated with decreased BMD, and the regulation of SOST levels via blood circulation affects bone metabolism, thereby contributing to the improvement of osteoporosis in patients with cirrhosis." (PMID 40563496, 2025). "The humanized sclerostin antibody, romosozumab, can significantly increase bone mineral density (BMD) of patients with osteoporosis, but it may also increase cardiovascular adverse events, particularly in male patients." (PMID 40464222, 2025). "Thus, targeting Wnt signaling pathway inhibitors, such as sclerostin, DKK1, WIF1, and SFRP, to regulate the expression of key molecules in the Wnt pathway represents a promising and safe therapeutic strategy for osteoporosis." (PMID 39606935, 2025). "Although anti‐sclerostin antibodies are clinically used for treating severe osteoporosis, this study did not confirm a direct anti‐sclerostin effect of BCAA intake in the human bone–muscle system." (PMID 41159395, 2025). "Currently, most osteoporosis therapies target osteoclasts to inhibit bone resorption, while the three FDA-approved anabolic agents include parathyroid hormone, parathyroid hormone-related protein, and anti-sclerostin antibody that promote osteoblast function." (PMID 41369394, 2025). "Among current drug treatments for osteoporosis, a range of options such as bisphosphonates, SERMs, PTH and its analogs, RANKL inhibitors, and Sclerostin inhibitors have been confirmed to effectively increase bone density, decelerate bone loss, and lower fracture risks." (PMID 38841589, 2024). "The FDA has approved various medications for the treatment of osteoporosis, including antiresorptive agent bisphosphonates, estrogen-related therapies, parathyroid hormone analogs, denosumab, a RANKL inhibitor, and romosozumab, a sclerostin inhibitor." (PMID 39452922, 2024). "An anti-sclerostin antibody is currently FDA approved as a treatment for osteoporosis and rare genetic diseases such as osteogenesis imperfecta, and the administration of PTH itself can reduce sclerostin levels." (PMID 38591777, 2024). "As of yet, there have been no studies of accomplished treatment of AN-related osteoporosis with romosuzumab, a monoclonal antibody to sclerostin." (PMID 39314548, 2024).
osteoporosis (continued). "So far, romosuzumab, a monoclonal antibody to sclerostin, has not been assessed in the treatment of AN-related osteoporosis in premenopausal women." (PMID 39314548, 2024). "Recent years have brought notable progress in osteoporosis treatments, including bisphosphonates, Selective Estrogen Receptor Modulators (SERMs), calcitonin, and parathyroid hormone (PTH) and its analogs, along with the newer Sclerostin inhibitors." (PMID 38841589, 2024). "Romosozumab, an anti-sclerostin treatment, presents a promising avenue for preventing and treating fractures in osteoporosis among postmenopausal women; however, potential negative cardiovascular effects need careful consideration." (PMID 38474734, 2024). "Intraperitoneal injection of 6A-8R attenuated ovariectomy-induced osteoporosis in mice by inhibiting osteoclast differentiation, promoting osteoblast differentiation, and inhibiting sclerostin production by osteocytes in vivo with no apparent side effects." (PMID 37991021, 2023). "Overall, while monoclonal antibodies to RANKL, Sclerostin, and DKK-1 for the treatment of osteoporosis are approved or in clinical trials, there is still a lack of knowledge regarding how to use these drugs effectively and which biomarkers must influence therapy selection." (PMID 37703870, 2023). "SOST and Dkk-1 can competitively bind to the co-receptor LRP5/6 in the Wnt signaling pathway and then regulate the transcription of downstream target genes, ultimately leading to the occurrence and development of osteoporosis." (PMID 36979418, 2023). "The monoclonal antibody romosozumab has been used to prevent vertebral compression fractures in patients with osteoporosis, and functions by blocking the activity of the LRP5 inhibitor, sclerostin, leading to an increase in LRP5-mediated canonical WNT signaling." (PMID 37895195, 2023). "Three previous studies have also shown a lower serum sclerostin concentration in patients with osteoporosis compared to non-osteoporotic patients." (PMID 35705746, 2022). "The goal of this study was to assess the plasma level of sclerostin and DKK-1 in patients with GD and correlate it with the degree of bone involvement, including bone pain, bone marrow infiltration, Erlenmeyer (EM) flask deformity, and osteoporosis." (PMID 36506070, 2022). "We also included blosozumab, another sclerostin inhibitor, which was investigated in osteoporosis trials but not approved for osteoporosis treatment at the time the present work was conducted." (PMID 35942681, 2022). "Serum sclerostin and irisin levels were significantly changed after ORX, which might be closely correlated with the occurrence of osteoporosis and sarcopenia in ORX rats." (PMID 36456918, 2022). "From another viewpoint, in femoral heads that did not receive treatment for osteoporosis, the activity of osteoclast and sclerostin increased at the osteocyte level." (PMID 36363523, 2022). "There is a study related to sclerostin and risedronate in mice, but as far as we know, there are no studies on bones from patients with fractures taking osteoporosis medications." (PMID 36363523, 2022). "Subjects with osteoporosis had a significantly lower mean serum sclerostin concentration compared to non-osteoporotic fracture patients (41.9 pmol/L SD 14.4 vs 48.1 pmol/L SD 17.5; p = 0.03)." (PMID 35705746, 2022). "However, the balance between sclerostin and DKK-1 waned in GD patients with osteopenia or osteoporosis." (PMID 36506070, 2022). "Three studies found a lower serum sclerostin concentration in patients with osteoporosis compared to non-osteoporotic patients." (PMID 35705746, 2022). "Others have investigated the use of novel bone markers from osteocytes (e.g., sclerostin and Dickkopf-1) in predicting osteoporosis and fracture, but without conclusive results." (PMID 36362662, 2022).
osteoporosis (continued). "Instead, higher DKK-1 and SOST levels were identified in RA patients without osteoporosis patients, correlating with high total hip and lumbar spine BMD, as well as with a decreased of major and hip osteoporotic fracture assessed by FRAX." (PMID 34497849, 2021). "Our main goal in this study was to determine if the interaction of sclerostin/Dkk1 coinhibition could be optimized to improve the osteoanabolic outcome over Scl‐mAb alone, which is an FDA‐approved strategy for the treatment of osteoporosis." (PMID 33977198, 2021). "In view of the specific role of osteocyte-related proteins such as DKK-1, SOST, and FGF23 in regulating bone health, it is tempting to speculate that their circulating levels could predict BMD, osteoporosis, and fracture." (PMID 32155909, 2020). "Although anti-sclerostin monoclonal antibody is expected for a novel therapeutic drug for the treatment of osteoporosis, there are no effective drugs for the treatment of both sarcopenia and osteoporosis at the present time." (PMID 32268570, 2020). "The proteins secreted by osteocytes, such as fibroblast growth factor-23 (FGF23), sclerostin (SOST), and dickkopf-1 (DKK1), could be candidates for osteoporosis screening and fracture prediction." (PMID 32155909, 2020). "Therefore, Wnt-signaling inhibitors, such as sclerostin and DKK-1, are promising for osteoporosis treatment." (PMID 31137666, 2019). "Therefore, the use of bispecific antibodies against both sclerostin and DKK-1 is expected to promote new bone formation more than monotherapy with an anti-sclerostin antibody, even in patients with osteoporosis." (PMID 31137666, 2019). "The purpose of the present study is to evaluate the relation between BMD and genotypes of four SNPs in previously reported osteoporosis candidate-genes (FDPS rs2297480, LRP5 rs3736228, SOST rs1234612, VKORC1 rs9934438) in a cohort of postmenopausal Romanian women." (PMID 31774873, 2019). "Sclerostin is a promising target and its inhibition has been shown to be beneficial in postmenopausal women and osteoporosis; however, currently there are no clinical trials for MM." (PMID 29098361, 2018). "The sclerostin inhibitor – AMG785 (Amgen Inc.)has protective effects against osteoporosis in preclinical studies and is in the clinical trials for treating postmenopausal women with osteoporosis." (PMID 29690863, 2018). "Sclerostin has been shown to be an important mechanism in osteoporosis; however, its importance has not been established in MBD." (PMID 29098361, 2018). "SPR4 suppression of sclerostin and/or sequestration of ASARM-peptides improves energy metabolism and may have utility for treating familial rickets, osteoporosis, obesity and diabetes." (PMID 24839967, 2014). "An antibody to SOST, romosozumab, is used to treat osteoporosis in patients, but may have negative effects on cardiovascular function." (PMID 39430425, 2024). "In chronic TSCI, sclerostin concentrations correlate with knee and hip BMD rather than time since injury and hence lower sclerostin levels may reflect increasing osteoporosis severity." (PMID 39320468, 2024). "Interestingly, our data suggest that sclerostin expression is very low in healthy postmenopausal women not affected by osteoporosis." (PMID 38598270, 2024). "These relationships were independent of BMD and bone turnover, suggesting that Sclerostin levels may reflectdisease-severity in osteoporosis." (PMID 38352898, 2024). "Furthermore, data for inhibition of sclerostin with monoclonal antibody romosozumab for treatment of osteoporosis is available for general population but not in KTRs which osteoporosis is highly prevalent." (PMID 39078512, 2024). "No reports have been made targeting sclerostin or DKK1 in osteoporosis in AD patients." (PMID 37635980, 2023).